IDH1 (isocitrate dehydrogenase (NADP(+)) 1)
Diseases named in the same sentence as IDH1 in open-access papers (continued):
Sharing a sentence is not in itself a finding about the gene and the disease.
cancer (continued). "In particular, the accumulation of 2-HG is a well-known hallmark in cancer cells and is generally attributable to the occurrence of gain-of-function mutation in IDH1 and IDH2." (PMID 29434411, 2017). "Lastly, some studies have confirmed that IDH1 mutated cancer cells have significantly low intracellular level of coenzyme NAD+." (PMID 28785398, 2017). "This study built upon a previous study demonstrating cancer-associated IDH1 mutations resulted in increased production of the oncometabolite 2-hydroxyglutarate (2HG)." (PMID 28653623, 2017). "In summary, the discovery of IDH1 or IDH2 mutations in human cancers has opened a window of opportunity for targeted therapies against cancers harboring these mutant enzymes." (PMID 27635066, 2016). "Despite their different physiological characteristics, most genomic studies of the molecular landscapes in human cancer have frequently combined IDH1 mutations and IDH2 mutations as a single functional group." (PMID 27245697, 2016). "This would indicate a potential therapeutic strategy to target oncogenic mTOR signalling in cancers harbouring IDH1/2 mutations." (PMID 27624942, 2016). "Our data raise the intriguing possibility that cancer therapeutic regimens designed to inhibit mutated IDH1/2 would be expected to reduce oncogenic mTOR activity." (PMID 27624942, 2016). "The most common cancer mutations map to single arginine residues in the catalytic pockets: IDH1 (R132) and IDH2 (R172 or R140)." (PMID 26812134, 2016). "Recent discoveries in the mutations of isocitrate dehydrogenases 1/2 (IDH1/2) in a large number of human cancers have provided a direct link between altered metabolism and cellular transformation and tumorigenesis." (PMID 25825982, 2015). "In IDH1- or IDH2-mutated cancers, the oncometabolite 2HG acts as a biomarker of compromised enzyme activity." (PMID 25632305, 2015). "To determine the function of D-2-HG in cancer cells, we aimed to eliminate D-2-HG in human cancer cells that contain a mutant IDH1 or IDH2 allele." (PMID 25825982, 2015). "More recently, the value of IDH1 inhibitors has now been established in pre‐clinical models as a possible anti‐cancer drug specifically active in IDH1 mutated cancer cells leading to delayed growth and the induction of differentiation." (PMID 25468711, 2015). "The IDH1 variants identified occur primarily in glial and hematologic malignancies, and result in altered cancer cell metabolism." (PMID 25656989, 2015). "Within the TCGA breast data set, two cancers (<0.5%) were found to harbor missense mutations in IDH1 that have a high probability of affecting the function of the enzyme (R132C, Y235C)." (PMID 25091696, 2014). "But the opposite enantiomer – the (R)-enantiomer, accumulates in adult cancer patients with somatically acquired mutations in IDH1 and IDH2." (PMID 24581008, 2014). "What is important for the current discussion is that the IDH1/2 mutational profile acts as a striking positive control, emphasizing the extraordinary capacity of human cancer to 'purify’ mutations that do provide selective advantage." (PMID 24491179, 2014). "Instead of the production of alpha-ketoglutarate, mutated IDH1 produced novel oncometabolite 2-hydroxyglutarate (2-HG) that was highly accumulated in the cancer cells." (PMID 24511544, 2014). "α-KG levels and total NADP+-dependent IDH activity were similar in IDH1-mutant and -wildtype xenografts, demonstrating that IDH1-mutated cancer cells maintain α-KG levels." (PMID 24252742, 2013). "To date, all reported IDH1 or IDH2 mutations are heterozygous, with cancer cells retaining one wild-type copy of the respective IDH1 or IDH2 allele." (PMID 23847760, 2013). "Various investigators working in the field of cancer genetics identified an increased incidence of heterozygous mutations in isocitrate dehydrogenase 1 and 2 (IDH1, IDH2) in selected individuals with carcinoma." (PMID 22391998, 2012).
cancer (continued). "The critical role the mutant allele is playing in cell survival strongly infers that mutant IDH1 can be used as a practical therapeutic target against IDH1 mutated cancers." (PMID 22885298, 2012). "The high frequency of IDH1 and IDH2 mutations in certain cancers, and the specificity of the genetic alterations to a limited set of amino acid residues, makes the mutant IDH1 or IDH2 product a tempting target for therapy." (PMID 22885298, 2012). "Based on this, IDH1 and IDH2 mutants have been proposed to inhibit the activity of the wild-type IDH1 or IDH2 allele in cancer cells in a dominant-negative fashion." (PMID 21326614, 2011). "The IDH1 mutations observed in cancer tissue are specific for R132, a residue in the enzyme active site." (PMID 21326614, 2011). "Many cancer studies already focused on IDH1 and IDH2 mutations." (PMID 39858052, 2025). "However, cancer-associated mutations, most commonly IDH1-R132H or IDH2-R140Q/R172K, confer a neomorphic enzymatic function." (PMID 40724998, 2025). "In cancers, mutations in IDH1 or IDH2 can result in the formation of D-2-hydroxyglutarate (2-HG)." (PMID 41235226, 2025). "In cancer cells, they are all upregulated or, like IDH1, activated by genetic mutations." (PMID 39996805, 2025). "Notably, IDH1 mutations are established cancer drivers through oncometabolite production, while PGAM1 enhances cancer cell survival by regulating glycolysis and biosynthesis pathways." (PMID 40861812, 2025). "Notably, in human cancers caused by mutations in IDH1, FH or SDH, the accumulation of metabolites in the TCA cycle, such as succinate and fumarate, is also frequently observed." (PMID 40523311, 2025). "IDH1 is overexpressed in many types of cancer and is closely associated with poor prognosis." (PMID 38674143, 2024). "Hence, loss of IDH1/2 results in impaired detoxification mechanism and aberrant methylation leading to increased DNA damage and genome instability in cancer cells." (PMID 38696033, 2024). "The discovery that mutations in isocitrate dehydrogenases (IDH1 or IDH2) could drive cancer development due to the abnormal generation of an oncometabolite 2-hydroxyglutarate is another example of the direct involvement of altered metabolism in carcinogenesis." (PMID 38658533, 2024). "IDH1/2 are the most frequently mutated cancer-associated metabolic genes." (PMID 39596840, 2024). "The presence of IDH mutations provides alternative therapeutic options including selective small molecule inhibitors (e.g. Enasidenib for IDH2 mutations and Ivosidenib for IDH1 mutations) which inhibit DNA hypermethylation and lead to delayed cancer cell growth and induction of cell differentiation." (PMID 38491228, 2024). "Mutations in IDH1 are responsible for the development and/or progression of various types of cancer due to the supraphysiological production of D-2-hydroxyglutarate (D2HG), which prevents cells from transforming into mature cells with normal functions and eventually causes cancer." (PMID 38622131, 2024). "Recent studies have also suggested that DMI may have applications in the detection and characterization of certain gene mutations associated with cancer, such as IDH1/2 mutations." (PMID 39165295, 2024). "In cancer cells, IDH1/2 mutations lead to excessive accumulation of 2-HG, which is an oncometabolite inducing biochemical and epigenetic alterations though competitive inhibition of a-KG-dependent enzymes including KDMs, PHDs, TETs, and ALKBH DNA repairs enzymes." (PMID 38696033, 2024). "Overall, the altered DNA methylation landscape has a central role in cancer, and targeting the epigenetic modifiers (e.g., DNMTs) and modulators (e.g., IDH1/2) involved in DNA methylation regulation can provide an avenue to modify cancer-associated transcriptional changes." (PMID 39766049, 2024). "In the present study, cancer patients with IDH1 mutation had high levels of D2HG, which could exacerbate proteolysis and induce cancer cachexia." (PMID 37741882, 2023).
cancer (continued). "Furthermore, the in vivo experiment showed that the IDH1 mutation in CT26 cancer resulted in high serum levels of D2HG, loss of lean body weight and skeletal muscle." (PMID 37741882, 2023). "Ivosidenib has been associated with IDH1 inhibition and has been studied in numerous cancers." (PMID 37692182, 2023). "Moreover, they also highlight wild‐type IDH1, and not only its mutated counterpart, as a potential therapeutic target for cancer treatment." (PMID 37086156, 2023). "With the analysis of cancer metabolism and genetics over the past two decades, IDH1 mutations not only lead to the accumulation of 2-hydroxyglutaric acid, but also to extensive changes in metabolic strategies, and metabolic reprogramming can be largely seen as a result of oncogenic driving events." (PMID 37274274, 2023). "2-Oxoacid–based inhibitors of cancer-associated IDH1/2 variants may complement currently used allosteric inhibitors whose efficacy can be reduced in patients because of inducing treatment-resistant second site IDH mutations." (PMID 36621625, 2023). "Idh1 has been extensively studied in the context of cancer and differentiation as it is tightly linked to TET function, which is essential in maintaining an stem cell state in healthy and malignant cells, underlining the biological significance of the quantified proteins." (PMID 37737208, 2023). "Somatic mutations in IDH1 and -2 occur in several cancers including AML." (PMID 37526143, 2023). "We suspected that the reason may be that the IDH1 inhibitor treated, ivosidenib, mainly targets the mutated IDH1 or that pan-cancer cells may take advantage of alternative pathways for lipid synthesis during this inhibition." (PMID 37958642, 2023). "Based on the mutation frequency, we imported R132H into a cancer cell and used an in vivo experiment to evaluate whether IDH1 mutation mediates D2HG accumulation during cancer cachexia progression." (PMID 37741882, 2023). "The combined kinetic results suggest that the substrate scope of cancer-associated IDH1/2 variants in cells may extend beyond 2OG, a proposal which requires further investigation via cell-based studies." (PMID 36621625, 2023). "However, mutations in either IDH1 or IDH2 occur in many other cancers, which can be a possible susceptible target by IDH mutant vaccination." (PMID 37296846, 2023). "The mutation in the cytosolic IDH1 enzyme at R132H, especially, may be associated with higher frequency of all types of cancers." (PMID 36903561, 2023). "We therefore tested the hypothesis that IDH1 mutation-mediated D2DH accumulation contribute to the progression of cancer cachexia." (PMID 37741882, 2023). "As such, it is tempting to speculate that IDH1 mutant ALT cancers may exhibit high levels of trapped PARP1 through loss of XRCC1 protein activity." (PMID 36940725, 2023). "Regarding the field of neurooncology, although some recent reports on establishing IDH1MUT high-grade cancer cell lines from corresponding mutated patient samples emerge, the establishment of IDH1 mutant in vitro models usually rely on genetic engineering of cells." (PMID 38086797, 2023). "The most common IDH1 variants in cancer cells are R132H and R132C11." (PMID 35970853, 2022). "In conclusion, the compound identified in this study had high selectivity for cancer cells harboring IDH1-R132C mutation and could be considered a promising hit compound for further development of IDH1-R132C inhibitors." (PMID 36160383, 2022). "For example, a pan-cancer analysis of bulk transcriptomics data reported that IDH1 mutations may be associated with gene signatures indicative of low B lymphocytes, NK cells, and T lymphocyte infiltration." (PMID 36142781, 2022). "The implications of IDH1/2 mutations vary greatly among different cancer types." (PMID 35526267, 2022). "However, cancer-associated mutations in IDH1 and IDH2 alter the activity of the mutant enzymes such that they produce the oncometabolite (R)-2-hydroxyglutarate ((R)-2HG)." (PMID 36056177, 2022).
cancer (continued). "Overall, cancer cells harboring IDH1/IDH2 mutations display hypermethylation of DNA and histone." (PMID 35935878, 2022). "The cellular inhibition assay demonstrated five compounds at a concentration of 10 μM could inhibit cancer cells harboring the IDH1-R132C mutation proliferation by > 50%." (PMID 36160383, 2022). "The identified compound T001-0657 could be a potential candidate for the treatment of cancers harboring IDH1 mutation." (PMID 36160383, 2022). "Cancer-linked substitutions at R132 of IDH1 (to H, C, S, L, G and V) involve shorter and less basic residues than arginine, consistent with weakened binding of isocitrate (and maybe CO2/bicarbonate) compared to wt IDH1, whilst still enabling 2OG binding." (PMID 34725432, 2021). "Furthermore, NAMPTi-induced NAD depletion in IDH1-mutant cancers was associated with inducing AMP kinase (AMPK) and initiating autophagy, and the autophagy inhibitor 3-MA rescued the cells from the cytotoxic effects of NAMPTi-mediated NAD depletion." (PMID 34068917, 2021). "The low frequencies of IDH1 and IDH2 mutations in human cancer were confirmed with MSK_Impact; the overall frequencies of IDH1 and IDH2 alterations were 3% and <1%, respectively; and IDH1 and IDH2 hotspot mutations were 2% and 0.3% (or 260 and 31), respectively." (PMID 34440884, 2021). "This metabolic deregulation may partially contribute to development of human cancer carrying oncogenic IDH1 and IDH2 mutations." (PMID 34516556, 2021). "Human cancer samples (solid tumors) analyzed for IDH1 and IDH2 gene mutations." (PMID 35996504, 2021). "These anti-cancer properties of chloroquine in combination with inhibition of autophagy by chloroquine may thus be selective for IDH1-mutated cells because it inhibits glutaminolysis and autophagy on which these cells are dependent." (PMID 34069550, 2021). "Indeed, mutant IDH1 was implicated in inducing methylation of LDHA promoter with a subsequent decrease of the gene upregulated in cancer cells and essential for glycolysis." (PMID 33923299, 2021). "Our analysis revealed that the overall prevalence of IDH1 mutations in cancer was 3%." (PMID 35996504, 2021). "We were able to confirm the clinical utility of ctDNA in IDH1-mutated cancers." (PMID 34069550, 2021). "Blockade of glutathione metabolism by NRF2 inhibitors results in potent suppression of IDH1-mutated cancer cells, which might indicate potential therapeutic approaches." (PMID 34571995, 2021). "Even though most studies suggested that D-2-HG suppresses DNA repair pathways, several studies indicated that IDH1/2 mutated cancers could up-regulate certain DNA repair mechanisms and develop resistance to chemo agents." (PMID 34571995, 2021). "Different forms of human cancer show mutations for isocitrate dehydrogenases 1 and 2 (IDH1/2)." (PMID 34946913, 2021). "However, even if IDH1 is a commonly mutated metabolic enzyme in some human cancers, only a recent report did describe IDH1 mutation in one patient with PDAC." (PMID 32756381, 2020). "Moreover, the gain of function mutations in specific isoforms of isocitrate dehydrogenase (IDH1 and 2), are also linked to cancer." (PMID 32985654, 2020). "Recently, alternations of IDH1 have been implicated in many types of cancer." (PMID 32373065, 2020). "The present study revealed that pathogenic IDH1 mutation contributes to cancer aggressiveness via prompting cellular food-seeking, motility, chemotaxis, and endocytosis, which resulted from the augmented mTORC2/Rac1 pathway and concomitant cytoskeleton mobilization." (PMID 32224866, 2020).
cancer (continued). "Our study provided proof-of-concept evidence that targeting the mTORC2/Rictor/Rac1 pathway could be useful to treat IDH1-mutated cancers." (PMID 32224866, 2020). "Understanding and predicting such constraints could have significant impact in both, the diagnosis (as seen for the polygenic risk scores for IDH1 mutations) as well as the treatment of cancer." (PMID 32239503, 2020). "Overall, we discovered that the acquisition of cancer-associated IDH1 mutant is associated with a distinctive transcriptional pattern, which may contribute to the unique food-seeking pattern." (PMID 32224866, 2020). "However, the most interesting target in the TCA cycle is IDH1/2: IDH1/2 is frequently mutated in aggressive cancers and contributes to various aspects of malignant growth, including also epigenetic regulation of DSB repair." (PMID 33202866, 2020). "The increased expression of IDH1 may be important, as IDH1 is frequently mutated in cancers and when mutated, it causes loss of α-ketoglutarate production and may be important for the Warburg effect." (PMID 32730293, 2020). "The 50 cancer gene panel detected an IDH1 mutation in one of the four patients (Patient 3)." (PMID 31795195, 2019). "Heterozygous somatic mutations in IDH1 or IDH2 genes have been detected in many cancers." (PMID 31105869, 2019). "The role of IDH1/2 mutations in cancer has been puzzling since their discovery." (PMID 31727977, 2019). "In addition, we revealed a high percentage of patients exhibiting elevated protein kinase activity of PGK1 compared to a relatively low IDH1 mutations in cancer patients." (PMID 31578148, 2019). "We hypothesized that DNA hyper- and hypomethylation changes that are common across all IDH1/2 mutated cancers of various tissues of origin may represent universal effect of the IDH1/2 mutations on the DNA methylation." (PMID 31727977, 2019). "The correlation between DJ-1 and the IDH-1 mutated form might be related to the activity of abnormal products of the metabolism of cancer cells since 2-HG contributes to metabolic reprogramming in diffuse glioma and hence to oxidative stress tolerance." (PMID 31434323, 2019). "Recent results on the activity of IDH1 mutation in cancer are contradictory." (PMID 30305430, 2018). "This assay could be used to distinguish between a mutant type and wild‐type, and thus, three recurrent oncogenic point mutations in genes KRAS, PIK3CA and IDH1 in human cancer cell lines have been identified." (PMID 30338908, 2018). "There is a renewed interest in the area of cancer metabolism with metabolic reprogramming coined as a hallmark of cancer based on the discovery of mutations and alterations in IDH1 and IDH2 along with succinate dehydrogenase (SDH), fumarate hydratase (FH), and pyruvate kinase M2 (PKM2)." (PMID 30024920, 2018). "These original discoveries led to a surge of sequencing studies reporting mutations in the IDH1 and IDH2 isozymes in AML and other cancers, and soon after, small molecule inhibitors targeting mutated IDH1/2 (mIDH) entered the clinic, which have produced exciting results." (PMID 29882807, 2018). "Frequencies of IDH1/2 mutations in different types of cancer." (PMID 30405699, 2018). "Similar to the IDH1 R132 mutation, the cancer-associated IDH2 R172 mutation was demonstrated to be deficient in isocitrate-dependent NADPH production, while acquiring a gain of function for alpha-ketoglutarate-dependent NADPH consumption that resulted in the production of 2HG." (PMID 28653623, 2017). "To gain a deeper understanding of the molecular mechanism(s) responsible for the preferential response of IDH1-mutated cancer cells to ABT263 treatment, we performed knockdown experiments with small-interfering RNA (siRNA) against Bcl-xL, a known major target of ABT263." (PMID 29057925, 2017).